ABCG2 (ATP binding cassette subfamily G member 2 (JR blood group))
Diseases named in the same sentence as ABCG2 in open-access papers (continued):
Sharing a sentence is not in itself a finding about the gene and the disease.
tumor (continued). "IHC studies revealed that ABCG2 is a component of the BBB and the blood–tumor barrier (BTB), where it functions as an efflux transporter." (PMID 38542090, 2024). "We also examined the toxic effects of LBP treatment on the visceral heart, liver, spleen, lungs, and kidneys as well as the expression levels of PMI, ABCG2, PI3K, and AKT in mouse tumor tissues." (PMID 38576495, 2024). "In this mechanism, a subset of EpCAM+/ABCG2+ cells (TSD+ CSCs) behave altruistically to protect the dormant R-CSCs, ultimately enhancing the overall fitness of the tumor." (PMID 39963656, 2024). "These cells showed elevated expression of the ATP-binding cassette (ABC) transporter ABCG2, proto-oncogenes c-Met and AKT, EMT marker N-cadherin, and tumor-initiating cell surface marker aldehyde dehydrogenase (ALDH) both in vitro and in vivo." (PMID 38509504, 2024). "Our present study demonstrates that lapatinib inhibits ABCG2-mediated PpIX efflux and sensitizes GBM cells to ALA-PDT by inducing tumor cell death." (PMID 39190205, 2024). "As per our working hypothesis, we expect all EpCAM+/ABCG2+ CSCs to exhibit altruistic behavior when exposed to a serum-free and hypoxic microenvironment that mimics the stressful microenvironment of intermittent hypoxia and oxidative stress prevalent in the tumor." (PMID 39963656, 2024). "While ABCG2 primary function is related to drug efflux, its expression can also be an indicator of a CSC population within the tumor." (PMID 38542090, 2024). "This expression pattern suggests a role for ABCG2 in the chemoresistant nature of these tumors and in maintaining the integrity of the BBB, even in the altered microenvironment of the tumor." (PMID 38542090, 2024). "Immunoblot of tumor bulk protein and in situ immunohistochemistry indicated that MIR31HG ASO therapy downregulated expression of GLI2, ABCG2, and SOX2." (PMID 37950038, 2024). "ABCG2 is well known for its ability to efflux a variety of chemotherapeutic agents, thereby conferring MDR on tumor cells in which it is overexpressed." (PMID 38641063, 2024). "We now report that ABCG2 interacts with SLC1A5, a member of the human solute transporter superfamily and the major glutamine transporter in tumor cells." (PMID 38641063, 2024). "Flow cytometry was used to collect GFP+ CD44+ CCs 14 d after tumor cell transplantation, and qRT-PCR was used to examine the expression of CSC markers (Oct4, Abcg2, Sox2, Bmi1, and Ssea1)." (PMID 38625488, 2024). "This protein subcomplex was identified in two different types of PCSCs, derived from PASC and PDAC neoplasms, which were phenotypically sorted based on their surface expression of CSC markers, including ABCG2, CD44, and CD133." (PMID 37709746, 2023). "IGF2BP3 is an RBP and can affect tumor progression by targeting mRNA for MMP1, CD44, CDK164, ABCG2, IGF2 and other genes." (PMID 37340423, 2023). "Hematoxylin and eosin (HE) staining of tumor tissue specimens, along with immunohistochemistry (IHC), were conducted to evaluate the expression levels of Ki67, GRP78, N-cadherin, Vimentin, and ABCG2." (PMID 37934581, 2023). "As expected, most tumor samples displayed expression of ABCB6, ABCG2, FECH and CPOX in our study, and expression was strongly correlated with fluorescence." (PMID 36612300, 2023). "Using fresh retinoblastoma tissue, the co-expression of EpCAM and three other putative tumor stem cell markers CD44, CD24 and ABCG2 was examined." (PMID 36132125, 2022). "The EGFR pathway is involved in the regulation of ABCG2 expression and function; in fact, EGFR inhibition led to the reversal of ABCG2-mediated chemoresistance in in vitro and tumor models." (PMID 35163586, 2022). "In tumor cells, activation of the ALA influx transporter of peptide transporter 1 (PEPT1) and inactivation of ABC superfamily G member 2 (ABCG2), which excretes PpIX, further exacerbates the accumulation of PpIX in tumor cells." (PMID 36195918, 2022).
tumor (continued). "Coexpression of ABCG2 and CD133 is a hint for identification of tumor-initiating cells in melanoma cancer." (PMID 35505363, 2022). "More importantly, several ABC transporters have been frequently found to be overexpressed in a variety of tumor resistant cells, such as P-glycoprotein (P-gp, ABCB1) and breast cancer resistance protein (BCRP, ABCG2)." (PMID 36120340, 2022). "To validate BIRC3 modulation of stemness genes in vitro, we further measured relative expression of CD133, ABCG2 and BMP4 using mRNA samples extracted from xenograft tumor tissues." (PMID 35008722, 2021). "It has been found that EMT tumor cells have the ability for self-renewal, unlimited proliferation and anti-apoptosis, and highly express CD133, CD44 + and ABCG2." (PMID 33992097, 2021). "Modified from a model of drug transport in tumor cells, we established a urate transport model of Caco-2 cells in vitro and found that estradiol could promote urate transport in Caco-2 cells, and this effect could be partially blocked by elacridar, as an ABCG2 inhibitor." (PMID 34144706, 2021). "It is believed that overexpression of ABC efflux proteins (e.g., P-gp/ABCB1, BCRP/ABCG2 and MRP/ABCC1) on the tumor cell membrane is one of the main mechanisms for this clinical resistance." (PMID 33918289, 2021). "In general, in the primary tumours, the ABCB1 was the dominant transporter and the expression levels of ABCG2 was markedly lower." (PMID 34065402, 2021). "Western blotting analysis revealed that six proteins (MGST1, MGST3, ABCG2, FXYD2, ALDH3A1, and GST-ω1) were differentially expressed among G1-G4 DDP-resistant tumor tissues." (PMID 32158694, 2020). "A significant reduction in tumor volume and weight occurred in the parental and ABCB1- or ABCG2-overexpressing tumors, compared to the single treatment groups." (PMID 32098067, 2020). "DPP-4-kd 4T1 tumors exhibited increased expression of P-gp, ABCG2 and MRP1 in primary tumors compared with that of control tumor-bearing mice, and this trend was enhanced in the presence of DOX." (PMID 31991851, 2020). "Overexpression of multiple ATP‐binding cassette (ABC) transporters such as ABCG2, MDR1 and Multidrug Resistance Protein 1 (MRP1) has been shown in the resistant tumour cells." (PMID 32633024, 2020). "The result showed a decreasing trend of ABCG2 and HIF‐1α in the aspirin and aspirin with cisplatin groups, which was consistent with the lightening of H460R tumor stemness, invasion and metastasis." (PMID 32991066, 2020). "Essentially, CRC tumor-spheres treated with MSI-N1014 showed significantly reduced expressions of LGR5, β-catenin, and ABCG2, and reduced resistance against 5-FU, with an increased level of microRNA (miR)-142-3p, which targets both LGR5 and ABCG2." (PMID 32560222, 2020). "In order to investigate the mechanism of action involved in the effect produced by the combinations, we analyzed the expression of ABCG2 and EGFR in tumor cells." (PMID 32911509, 2020). "ABCG2 is a member of the superfamily of ATP-binding cassette (ABC) transporter protein, which can induce drug resistance and treatment failure in tumor tissues." (PMID 33050883, 2020). "The protein expression levels of MGST1, MGST3, ABCG2, and FXYD2 differed among the G1-G4 DDP-resistant tumor tissues." (PMID 32158694, 2020). "High ABCG2 expression corresponded to HNC stemness, tumor grade, and clinical outcome, showing that ABCG2 is important in controlling ALA-PDT efficacy to treat HNC." (PMID 32957726, 2020). "Further study revealed that DD promoted tumor growth and metastasis by activating the AKT signaling pathway followed by an increased ABCG2 expression." (PMID 32742477, 2020). "Substrates of BCRP (ABCG2) include glutathione and steroid hormones as well as some anti-tumor chemotherapeutic agents like methotrexate, mitoxantrone, and topotecan (Huang & Sadée, 2006), which overlap with those of P-gp." (PMID 31928355, 2019).
tumor (continued). "Finally, our data suggest that inhibition of essential residues in the ABCG2 roof or in the di-leucine valve could hold promises for therapeutic intervention in case of drug-resistant neoplastic diseases, where ABCG2 has been notoriously known for playing detrimental roles." (PMID 31780715, 2019). "In four subjects (p01, p02, p03 and p05), surgically resected tumor tissue was analyzed for ABCB1 and ABCG2 levels with QTAP." (PMID 31832814, 2019). "In 88 advanced-stage serous EOC samples, the percentage of cells positively stained for ABCG2 and SIK3 in the tumor region was scored and analyzed." (PMID 31762812, 2019). "The stemness‐associated genes were analysed using RT‐qPCR, and the results showed that the mRNA levels of Nanog, Sox2, Oct4, CD44, CD133, ABCB1, ABCC1, ABCG2 and Notch1 were significantly increased in RCC tumour spheres compared with parental cells." (PMID 30246456, 2018). "These tumor-propagating cells are featured with higher expression levels of NPM-ALK and ATP-binding cassette transporter G2 (ABCG2) as compared to bulk cell populations." (PMID 29609590, 2018). "ABCG2 and ABCB1 are expressed not only in tumor tissues but also in normal tissues including the liver." (PMID 30326853, 2018). "Immunostaining revealed that ABCG2 and ALDH1 markers were highly expressed in 76.2% and 80.0% of cancerous tissues as compared to 28% and 33% of benign tumor tissues, respectively." (PMID 31516883, 2018). "Recently, we showed that nilotinib reversed ABCB1- and ABCG2-mediated MDR to paclitaxel and DOX, respectively, in nude mouse tumor xenograft models." (PMID 29212189, 2017). "In this study, we firstly mined and discovered aberrant expression of ABCG2 in GC patients from NCBI database, which directed us to conduct further investigation in both GC tumor tissues and cell lines." (PMID 28029654, 2017). "ABCG2 expression significantly correlated with TNM stage, tumor differentiation, and lymphovascular invasion." (PMID 28212529, 2017). "Of note, high expression of MDR-1, P-gp, ABCG2 and GST-πwas found in many tumor cells and tissues including gastric, lung, colorectal, breast and prostate cancers." (PMID 29137307, 2017). "In parallel with these signatures, HaCaT-Piwil2 cells, which had acquired tumor-initiating capability, expressed the TIC markers ALDH, MSCA-1, and ABCG2 and generated highly aggressive tumors when injected into mouse oxters." (PMID 27602489, 2016). "In contrast to the ABCC1 promoter which was found to be hypomethylated (methylation status < LOQ) in all tumor, tumor-adjacent and tumor-distant tissues, the ABCB1 and ABCG2 promoters were found to be methylated very frequently." (PMID 27689338, 2016). "ABCG2, Cul3, IGFBPR5, PTEN, and SPARC genes levels of expression were related to the malignant phenotype in tumor cells, and those differential expressions were found to be modulated by Maitake in our previous studies." (PMID 27401257, 2016). "Classical MDR is characterized by upregulation of ABC transporter genes, such as ABCB1 and ABCG2, that transport anticancer agents out of the cell and confer tumor cell resistance to those drugs." (PMID 27050375, 2016). "Two of these transporters, ABCG2/BCRP and ABCB1/MDR-1, are reported to be the principal sources of the SP phenotype in human tumor cell lines." (PMID 26859746, 2016). "To investigate the role of CSCs markers in TNBC cancerogenesis and tumor progression, we selected 160 TNBCs samples on which we detected protein expression of CD44, CD24, CD133, ALDH1, and ABCG2 by immunohistochemistry." (PMID 26504780, 2015). "Using PDAC datasets of the NCBI Gene Expression Omnibus (GEO, GSE28735) database, ErbB2, hCNT1, hCNT3, ABCG2, MRP1 and MRP2 mRNA expression was measured in 45 tumors (T) and adjacent non tumor tissues (ANT)." (PMID 25890497, 2015). "Here, we have designed and synthesized ABCG2-siRNA to specifically and effectively down-regulate breast cancer resistance-related protein (BCRP) expression in tumor cells in vitro." (PMID 26575421, 2015).
tumor (continued). "Detailed phenotypic and molecular profiling in Du145 and LAPC9 models shows that the CD44+, α2β1+, ABCG2+, and ALDH+ cell populations identify overlapping subsets of tumor-initiating cells." (PMID 26246472, 2015). "The in vivo gene silencing of ABCG2-siRNA-loaded PEAL NPs was evaluated in animals bearing MCF-7/S and MCF-7/ADR tumor xenografts." (PMID 26575421, 2015). "Mesospheres, typified by the stemness markers CD24, ABCG2 and OCT4, initiated tumours in immunodeficient mice more efficiently than adherent cells." (PMID 25932953, 2015). "On the other hand, miR-320 was reported to inhibit the Wnt/β-catenin pathway in PC3 and DU145 cells with concurrent reductions in the cell-derived xenograft tumor formation in NOD/SCID mice, as well as the CD44+ cell subpopulation, Oct4 and ABCG2 expression." (PMID 26593949, 2015). "In contrast, mRNA expressions of ABCC3 (MRP3) and ABCG2 are induced, which may be important for the efficacy of chemotherapeutics when these drugs’ intestinal absorption (assuming oral administration) or transport out of the tumor cell is modulated by MRP3 or BCRP, respectively." (PMID 25521244, 2014). "One goal of researchers is to counter the drug resistance of tumor cells and improve drug sensitivity by modifying the BCRP/ABCG2-mediated, drug-resistant phenotype and the drug-resistant phenotypes of ABC membrane transporter families." (PMID 25076217, 2014). "After intraperitoneal injection of BCRP/ABCG2-tolerant 5-FU, the tumor volume, weight change, and apoptosis rate of the tumor tissue were determined using in situ hybridization." (PMID 25076217, 2014). "The results showed that ISL with or without epirubicin significantly inhibited miR-25 expression in the tumor tissue; this was accompanied by increases in the expression of LC3-II, ULK1 and BECN1 as well as a decrease in the expression of ABCG2." (PMID 25026296, 2014). "We also exploited Ki-67 to detect the proliferative activities of tumor cells in ACC, and we noticed that ABCG2 was also expressed in the same location with Ki-67-positive cells." (PMID 24804195, 2014). "We evaluated the tumor growth inhibition data and ABCB1 and ABCG2 gene expression data and found a significant correlation with ABCB1 (p = 0.02), but not with ABCG2 (p = 0.7), reinforcing what was observed in vitro." (PMID 23524533, 2013). "ABCG2, or Breast Cancer Resistance Protein (BCRP), recognizes and carries several conventional anti-tumor drugs, including small chemotherapy molecules." (PMID 23976904, 2013). "We observed that a subpopulation of tumor cells in all the samples showed dual expression of EpCAM with CD44, CD24 and ABCG2 individually." (PMID 22328825, 2012). "To determine if LMWH affets ABCG2 expression at the mRNA level, we performed qRT-PCR analysis of SP cells treated with LMWH for 16 hours and tumor cells from LMWH treated and control mice." (PMID 22844424, 2012). "We studied the expression of proteins that possibly affect ALA-mediated PpIX accumulation, namely oligopeptide transporter-1 and -2, ferrochelatase and ATP-binding cassette transporter G2 (ABCG2), in several tumor cell lines." (PMID 23189181, 2012). "Two well known genes, ABCG2 and ABCA5 that involved in drug resistance in many types of tumor were overexpressed in CD44H cells." (PMID 21731740, 2011). "These two types of tumor cells share the common marker CD44+, but they can be distinguished by other well-defined markers including ABCG2+ and α2β1+, which are specific for tumor progenitors." (PMID 20052382, 2009). "Collectively, these data demonstrated that KSQ‐4279 could widely and significantly potentiate the chemotherapeutic cytotoxicity of traditional agents in the ABCB1‐, ABCG2‐, and ABCC1‐induced MDR tumor cells in vitro." (PMID 41328326, 2025).
tumor (continued). "Our study demonstrates that the ferroptosis inducer, Erastin, exhibits strong cytotoxicity against ABCB1- and ABCG2-expressing tumor cells, indicating it is not a substrate for these ABC transporters in NCI/ADR-RES and MCF-7/MXR cells." (PMID 39859349, 2025). "ABCG2+tumor cells may represent a distinct CSC population with inherent resistance to common antitumor drugs, potentially contributing to tumor recurrence." (PMID 41368628, 2025). "Concurrently, the co-delivery of DOX and miR-519c through MDPAS micelles can reverse the MDR effect by inhibiting the efflux of ABCG2-dependent drugs and increasing the intracellular concentration of DOX as a result enhancing the inhibition of tumor growth and achieving optimal therapeutic effect." (PMID 38735927, 2024). "In addition, other mechanisms like tumor heterogeneity and co-expression of ABC transporters ABCG2, P-gp, and MRP1 with overlapping substrate specificities pose further challenges to overcome MDR." (PMID 39403604, 2024). "Importantly, AF+ cells were more tumorigenic than AF– cells, as we have previously shown, and AF was reduced when tumor cells were incubated with FTC, altogether confirming that the AF cells are bona fide CSCs and the AF observed was ABCG2 dependent." (PMID 39225547, 2024). "Regarding patient survival, the ABCG2 score affected patient survival overall but not in relation to chemotherapy and radiotherapy, and the level of ABCG2 tumor cell expression did not affect patient survival." (PMID 38542090, 2024). "Moreover, EpCAM+/ABCG2+ cells obtained from the BM tumor spheroids (Cisplatin ++ group), when injected to mice, showed induction of TSD phenotype similar to the parental EpCAM+/ABCG2+ cells." (PMID 39963656, 2024). "Nor does it explain observations made in the clinic, where the expression of ABCG2 has been correlated with tumor survival and poor prognosis independent of drug treatment." (PMID 38641063, 2024). "Tumor stem cell (CSC) pluripotency markers include CD133, ABCG2, and ALDH1A1." (PMID 38576495, 2024). "Studies have demonstrated that ABCG2 is not uniformly distributed across all tumor cells but is predominantly found in CSCs and in cells forming the BBB." (PMID 38542090, 2024). "The MP2 fraction seemed to contain a highly proliferative group of cells that were well differentiated and the least aggressive, signifying that this fraction was enriched for hyperplastic tumor cells that lacked ABCG2 and MDR1 drug transporter proteins." (PMID 36834918, 2023). "Furthermore, the primary CRC cells were obtained from the formed xenograft tumor masses, and the same results were shown in the ability of spheroid formation and colony formation as in vitro upon TOX3 knockdown and/or ABCG2 overexpression." (PMID 37708089, 2023). "In one study, neither cytoplasmatic nor membranous expression of ABCG2 protein was found to be connected with age, sex, tumour site or TNM stage; however, higher expression in both localizations was linked with more pathologically differentiated lesions." (PMID 37445716, 2023). "ABCB1, ABCC1\2\3, ABCG2, ERCC1, XRCC1\2 can induce tumor chemo-resistance and radio-resistance." (PMID 37283789, 2023). "Our findingsrevealed that flunarizine did not affect ABCB1 and ABCG2 transportactivity.Consistent with these findings, flunarizine also did not appreciablyaffect the plasma concentration and tumor accumulation of gefitinibin the PDX animal study." (PMID 37854628, 2023). "In addition, in SW480 cells, knockdown of ABCG2 by lentivirus construct inhibits CD133 expression, sphere formation in vitro and tumour formation in vivo." (PMID 37445716, 2023). "Compared with normal tissues, whether ABCG2, TOX3, or WDR5 is up-regulated in clinical metastatic and drug-resistant tumor specimens, and shows a strong prognostic value for OS and DFS in drug-resistant CRC patients." (PMID 37708089, 2023).